CDK4 (cyclin dependent kinase 4)
Diseases named in the same sentence as CDK4 in open-access papers (continued):
Sharing a sentence is not in itself a finding about the gene and the disease.
cancer (continued). "It activates CDK4/6 upon transcription signals activated via mitogenic or growth factors and is dysregulated in various cancers." (PMID 36769170, 2023). "Cyclin D1 is an abnormally expressed maker in cancers which promotes the G1 to S phase transition by binding to CDK4." (PMID 35224100, 2022). "Given their position as relatively upstream regulators of these crucial cell cycle pathways, CDK4/6 specific inhibitors have become very attractive cancer therapeutic agents." (PMID 35936751, 2022). "CDK4 expression is also a prognostic indicator in certain cancers, such as triple negative breast cancer (TNBC)." (PMID 36051751, 2022). "More recently, a study demonstrated that HPVneg HNSCC cancer cells harboring a mesenchymal phenotype were less sensitive to CDK4/6 inhibition than those with an epithelial phenotype." (PMID 35546399, 2022). "Among the top 10 cited articles worldwide, the article with the highest LC/GC ratio is “Early Adaptation and Acquired Resistance to CDK4/6” published in Cancer Research in 2016 by Herrera-Abreu MT from the UK as the first author." (PMID 36530984, 2022). "Based on CDK4/6 inhibitor suppressing immune evading, the regimen of abemaciclib plus cancer immunotherapy, such as humanized antibody targeting the programmed cell death protein 1 (PD-1) receptor of lymphocytes pembrolizumab, has entered clinical trials." (PMID 35785151, 2022). "Loss of the p16INK4A function is also a common event leading to dysregulation of the Cyclin D–CDK4/6 axis in cancer cells, as it can predict strong CDK4/6 dependence in cancer cells." (PMID 35892870, 2022). "To summarize, the clinical significance of this article is to focus on the efficacy of CDK4/6 inhibitors in prolonging the life span of patients by inhibiting the growth and proliferation of cancer cells." (PMID 35530846, 2022). "In in vivo studies LPM3770277 demonstrated significant anti-TNBC cancer efficacy and superior safety as compared to the clinically used CDK4/6 inhibitor abemaciclib." (PMID 35479314, 2022). "Several studies have shown that in addition to a direct effect on cancer cells, CDK4/6 inhibitors can enhance expression of surface MHC-I on certain tumors, thus making the cells more visible to the immune system." (PMID 35562811, 2022). "The last component, cyclin D1, is frequently dysregulated in many human cancers, acting as an allosteric modulator of cyclin-dependent kinase 4 and 6 (CDK4/CDK6) and regulating the transition of G1 to S phase." (PMID 35448172, 2022). "For example, BRAF and CDK4, members of the Ser/Thr kinase, up-regulated in cancer, displayed changing connectivity patterns from stages I to IV." (PMID 35448980, 2022). "Our data show that in spite of the opposing roles in cell cycle regulation, a combination of the oncolytic adenoviruses and CDK4/6i acts synergistically by increasing viral genome replication and cancer cell lysis." (PMID 35948546, 2022). "Palbociclib is the first selective CDK4/6 inhibitor approved for cancer treatment and is used for estrogen receptor-positive/human epidermal growth factor receptor-2 (HER2)-negative metastatic breast cancer." (PMID 36003796, 2022). "Several selective CDK4/6 inhibitors such as palbociclib, ribociclib, and abemaciclib have been developed and widely used in preclinical and clinical trials for cancer treatment." (PMID 36432068, 2022). "A better understanding of the mechanisms regulating senescence induced by CDK4/6 inhibitors is needed in order to increase therapy efficacy and patient stratification in cancer." (PMID 35184131, 2022). "As a result, it was Cyclin D1 and CDK4 expression levels were downregulated during the G0/G1 arrestment in the cancer cells." (PMID 36263164, 2022).
cancer (continued). "Currently, the mechanisms involved in the reversal of MDR cancer by CDK4/6 inhibitors remains to be elucidated." (PMID 35450042, 2022). "CCDC68 is a putative tumor suppressor gene in several types of cancer, partly through regulating the cell cycle by controlling the degradation of CDK4." (PMID 35976950, 2022). "In recent years, CDK4/6 inhibitors have continued to be applied to the clinical trials of various malignant tumors." (PMID 35621970, 2022). "Recent advances in biomarker identification are discussed, including the potential use of liquid biopsy for BC management and the role of multiple microRNAs as molecular predictors of cancer cell sensitivity and resistance to CDK4/6 inhibitors." (PMID 36498861, 2022). "CDK4/6 inhibitors treat cancer by targeting cyclin-dependent kinases 4 and 6 (CDK4 and CDK6) to trigger cell arrest and halt cell cycle progression." (PMID 36515302, 2022). "The anti‐cancer effects of CDK4/6i are mainly driven by the induction of cancer cells into senescence." (PMID 34985783, 2022). "CDK4/6 inhibitors effectively arrest cancer cell proliferation in the G1-phase by inhibition of Rb phosphorylation." (PMID 36432068, 2022). "Cyclin D1, with its partner CDK4/6, plays a dominant role in regulating G1/S cell cycle progression of various cancer cells." (PMID 35078428, 2022). "Some studies demonstrated that many tumorigenic events ultimately drove cancer cell proliferation by regulating CDK4 or CDK6 complexes in the G1 phase of cell cycle." (PMID 36408174, 2022). "CDKN2A, also known as multiple tumour suppressor 1, is an inhibitor of CDK4 that suppresses cancer cell proliferation by arresting the cell cycle at phase G1." (PMID 35459137, 2022). "Evidently, it is likely that the combinations of selinexor and KRAS G12C inhibitors induce cell-cycle arrest in KRAS G12C–mutant cancer cells by downregulating cyclin B1 and CDK4 expression and upregulating the accumulation of TSP Rb in the nucleus." (PMID 35573474, 2022). "Remarkably, CDK inhibitors, such as CDK4/6 inhibitors, are already used in preclinical studies for cancer treatment." (PMID 36292630, 2022). "Abemaciclib (ABE), ribociclib (RIB), and palbociclib (PAL) are CDK4/6 inhibitors that work by targeting overactive CDK4/6 in cancer cells and stopping their cell cycle, thereby slowing proliferation." (PMID 36364432, 2022). "Studies in several in vitro and in vivo cancer models have demonstrated that the CDK4/6 inhibitor palbociclib can stimulate PD-L1 expression on cancer cells and induce immune cell infiltration in the TME." (PMID 35884422, 2022). "Since this pathway is often deregulated in cancer, several inhibitors directed against CDK4/6 (CDK4/6i) have been developed to prevent phosphorylation of RB11." (PMID 35948546, 2022). "FDLE arrested cancer cells at the G0/G1 phase by downregulating p-NF-κB, cyclin D1 and CDK4, while upregulating p21 in both normal growth and inflamed HCT-116 and HT-29 cells." (PMID 35681644, 2022). "The CDK4/6i are exciting new drugs for cancer therapy, and ongoing studies and trials surely will add new mechanistic understanding to and improvement of clinical outcomes." (PMID 36185294, 2022). "Despite the recognition that transcriptional addiction is a valid target for cancer therapy, the cell cycle related CDKs, most prominently CDK4/6, have received more attention in terms of development as therapeutic targets." (PMID 36577800, 2022). "Due to its evident role in proliferation and cancer, several CDK4/6 inhibitors have been generated, including palbociclib and ribociclib, which specifically target CDK4/6, and abemaciclib which targets CDK4/6 and other similar kinases." (PMID 35911672, 2022). "In conclusion, the results showed that VHL and cIAP-based degraders were an attractive approach for targeted degradation of CDK4/6 in cancer." (PMID 35680848, 2022).
cancer (continued). "It is well known that genetic CDKN2A inactivation contributes to malignant transformation, cancer metastasis, and therapeutic sensitivity of cancers to drugs, including CDK4/6 inhibitors and their combination with PD-1 blockade." (PMID 36531022, 2022). "Combination of CDK4/6 inhibitors and immunotherapy is another strategy to induce anti-cancer immune responses by using anti-PD-1/PD-L1 inhibitors." (PMID 35938171, 2022). "Constitutive activation of the complex of cyclin D and CDK4/6 results in uncontrolled cell proliferation, and has a strong link to many cancers." (PMID 35911672, 2022). "Expression levels of cell-cycle markers such as CDK4 and cyclin B1 were also found to be reduced in both the cancer cell lines as a result of treatment with KRAS G12C inhibitors or their combinations with selinexor." (PMID 35573474, 2022). "Thereby BETi’s sensitizes cancer cells, even in RB1-deficient cells, to CDK4/6 inhibitors, which have currently been approved for the treatment of hormone-positive breast cancers." (PMID 36139513, 2022). "As the Rb/E2F pathway is frequently deregulated in cancer, E2F inhibition using CDK4/6 inhibitors are widely explored as therapeutic agents in cancer." (PMID 35058574, 2022). "CDK inhibitors, in particular CDK4/6 inhibitors (Abemaciclib, Palbociclib and Ribociclib), induce cell-cycle arrest and subsequent senescence in several cancer cell lines and mouse models." (PMID 35821824, 2022). "Palbociclib, also known as PD 0332991, was the first CDK4/6 inhibitor to be approved in cancer therapy." (PMID 35053461, 2022). "In many cancer entities, the CDK4/RB1 pathway is disturbed and leads to increased cell proliferation." (PMID 34687436, 2022). "Previous research has described the role of cyclin D1 and CDK4 in augmented cell proliferation and poor prognosis in some types of cancer." (PMID 35448172, 2022). "While the selective CDK4/6 inhibitors show promising targeted therapy for cancer treatment, the onset of therapeutic resistance to these agents through both intrinsic and acquired molecular mechanisms has been encountered in cancer treatment." (PMID 35892870, 2022). "Fascaplysin is isolated from sponges and exerts anticancer effects by inhibiting cyclin-dependent kinase 4 (CDK4), whose effects include growth inhibition, angiogenesis, metastasis, and proliferation of several cancer cells." (PMID 36430250, 2022). "CDK4 and Cyclin D are key players controlling regulation of the G1-S checkpoint and often undergo dysregulation in cancer cells." (PMID 36672573, 2022). "The CDK4/6‐Rb axis is a crucial target of cancer therapy and several selective inhibitors of it have been approved for clinical application." (PMID 35711853, 2022). "Cancer is characterized by uncontrolled proliferation resulting from aberrant activity of various cell cycle proteins, such as CDK4 and CDK6." (PMID 35859766, 2022). "The specific role of autophagy in cancer cells remains controversial and highly context-dependent; indeed the autophagic process has been described as a mechanism of resistance to CDK4/6 inhibitors as well as an inducer of cell death." (PMID 36497412, 2022). "As a result, the vast majority of studies on CDK4/6 inhibitors have focused on RB-proficient cancer cells." (PMID 35892870, 2022). "Due to the importance of CDK4/6 activity in cancer cells, CDK4/6 inhibitors have emerged as promising candidates for cancer treatments." (PMID 35270034, 2022). "CDK4/6i block cancer cell growth at the G1 phase of the cell cycle, while paclitaxel (and additional taxanes) targets cancer cells at the M phase." (PMID 36185294, 2022).
cancer (continued). "In cancer cell lines, p21 acts as an activator to synthesize and activate cyclin D/Cdk4 or Cdk6 complexes to enhance proliferation efficiency." (PMID 36057545, 2022). "For example, we found that CDK12 is essential in ~ 30% of cancer cell lines with average effects that were similar to those of CDK4 and CDK6." (PMID 36577800, 2022). "In the cases of lung cancer cells, addition of paclitaxel first followed by CDK4/6i had higher cancer cell killing than the reversed sequence." (PMID 36185294, 2022). "By inhibiting kinase activity, CDK4/6 inhibitors are able to block cell-cycle progression from phase G1 to phase S and prevent the progression of cancer cells." (PMID 35884422, 2022). "In agreement with this notion, our results showed that continuous pressure from CDK4/6 inhibition is needed to produce optimum anti-cancer activity." (PMID 35664774, 2022). "An in silico study on three main enzymes EGFR, CDK2 and CDK4 proved the effectiveness of trans-anethole in inhibiting these enzymes and so the consequences of cancer progression." (PMID 35850583, 2022). "Several clinical trials using CDK4/6 inhibitors in various cancer types, such as non-small cell lung cancer, ovarian cancer and triple negative breast cancer were recently completed." (PMID 36067171, 2022). "A key characteristic of cancer cells is the deregulation of cell cycle checkpoint proteins such as the cyclin-dependent kinases (CDKs) CDK4 and CDK6 leading to uncontrolled cell proliferation." (PMID 35821824, 2022). "Meanwhile, two studies demonstrated that lidocaine inhibited cancer migration and enhanced the efficacy of the cyclin-dependent kinase 4/6 inhibitor palbociclib in TNBC." (PMID 36555096, 2022). "Understanding CDK regulation has important biomedical implications, a well‐known example of this gene family is that pharmacologic CDK4/6 inhibitors have shown their ability to fight against several solid tumors by inducing cancer cell apoptosis or senescence." (PMID 34687270, 2022). "Statins suppress cancer cell proliferation by inducing cell cycle arrest through the regulation of cyclin-dependent kinase 4/6 (CDK4/6) or cyclin D1." (PMID 35164691, 2022). "Recent evidences have suggested that, similar to what observed for cancer cells, prolonged treatment with CDK4/6i can promote the premature senescence of non‐malignant cells." (PMID 34985783, 2022). "In an effort to expand the utility and benefits of immune checkpoint therapy to breast and other cancers, several groups have exploited the immunomodulatory properties of CDK4/6 inhibitors to enhance the efficacy of immune checkpoint inhibitors." (PMID 36051751, 2022). "Imbalance in the activity of CDK4 and CDK6 can induce dysregulation and uncontrolled cell division, which is a hallmark of cancers." (PMID 35459184, 2022). "Similar effects are observed in a range of cancer lines, which demonstrates that the induction of genotoxic stress is a common outcome of targeted CDK4/6 inhibition." (PMID 35037284, 2022). "Our results demonstrate that cancer patients under targeted therapy with either CDK4/6, PARP inhibitors or ARTA have lower levels of NAb after vaccination compared to healthy controls at all timepoints." (PMID 36146552, 2022). "mmp1 promotes cell cycle acceleration in cancer cells by activating the cdc25a/CDK4-cyclin D1 and p21/cdc2-cyclin B1 complexes." (PMID 36225568, 2022). "Since Rb pathway plays a critical role in senescence, CDK4/6 inhibitors have ability to induce senescence in cancer cells." (PMID 35814226, 2022). "Cyclin D1 and CDK4/6 (cyclin-dependent kinases 4 and 6) proteins are responsible for progression through G1 to S phases, a step which is often deranged in many cancers, including mesothelioma." (PMID 36232554, 2022). "CDK4 inhibitors effectively block the proliferation of cancer cells by inducing G1 phase cell cycle arrest." (PMID 36699068, 2022).
cancer (continued). "The rapidly accumulating information should allow the contemplation of strategy and design of rationale combinatorial therapies of CDK4/6i with other anti-cancer agents to overcome drug resistance and achieve superior treatment outcomes." (PMID 36185294, 2022). "Cyclin D1, a mitotic sensor and allosteric activator of CDK4/6, is one of the most common cell cycle regulators in cancer and is often overexpressed in cancer." (PMID 36379920, 2022). "Dysregulation of the Cyclin D–CDK4/6 axis through various mechanisms leads to uncontrolled cell proliferation, frequently shown in many types of cancer, which are thought to show greater dependency on CDK4/6." (PMID 35892870, 2022). "In the G1 phase of the cell cycle, the CDK2-cyclin E and CDK4/6-cyclin D complexes phosphorylate the tumor suppressor RB protein, resulting in its inactivation and the acceleration of cancer cell proliferation." (PMID 35681048, 2022). "While CDK4/6 inhibitors can induce quiescence, they also can trigger senescence in various cancer cells." (PMID 36065138, 2022). "Further, the CDK4/6i Palbociclib has been shown to induce senescence in a variety of cancer cell lines that express functional retinoblastoma protein (pRB) as well as in solid tumors in vivo." (PMID 35158840, 2022). "The homolog-specific functions, especially those in cancer cells, make the CDK4- and CDK6-specific therapeutic agents highly desirable." (PMID 35327487, 2022). "Mechanistically, Palbociclib inhibits CDK4/6 activity but the basis for differing sensitivity of cancer to Palbociclib is poorly understood." (PMID 35817775, 2022). "CDK4/6 inhibitors (CDK4/6i) and oncolytic viruses are promising therapeutic agents for the treatment of various cancers." (PMID 35948546, 2022). "Cyclin D1 and CDK4 were found to mediate therapeutic resistance to HER2 blockade in HER2-positive cancers." (PMID 36387174, 2022). "This is in line with the notion that cancer patients tolerate CDK4/6 inhibitors better than standard chemotherapies." (PMID 35775492, 2022). "For example, CDKN2A, E2F1, E2F2, and CDK4 were significantly overexpressed in 28, 26, 24, and 15 cancers, respectively." (PMID 35911954, 2022). "ribociclib is a CDK4/6 inhibitor that reduces RB phosphorylation and, as a result, suppresses cancer cell proliferation." (PMID 36548336, 2022). "Overall, the evidence shows that investigation of miRNAs as predictive biomarkers of CDK4/6 activity in BC and other cancer types is at an embryonic stage." (PMID 36498861, 2022). "MDM2 inhibitors have been reported to combine with other agents for cancer therapies, such as CDK4/6 inhibitors and 5-azacitidine." (PMID 36180435, 2022). "The ability of CDK4/6 inhibitors to induce genotoxic damage as a result of replication stress has important implications for cancer treatment." (PMID 35037284, 2022). "Abnormal expression of CDK4/6 in various cancers can lead to dysregulation of the G1-S checkpoint of the cell cycle to promote cancer cell proliferation." (PMID 36620587, 2022). "Based on past reports, the dysregulation of the cyclin D1/CDK4/6 pathway is crucial for cancer tumorigenesis as this is involved in cell cycle progression." (PMID 36233758, 2022). "It is reasonable to believe that ARF-based therapies can provide synergistic effects with CDK4/6 inhibitors, especially in CDKN2A-deficient cancers." (PMID 35155432, 2022). "Here, we characterized CDK4 which is activated in many cancer cells and against which a potent and specific inhibitor (Palbociclib) is available." (PMID 35054996, 2022). "The enhancement of cyclin D1 expression and cyclin-dependent kinase activation in SEMA6C-low cancer created a druggable target of CDK4/6 inhibitors." (PMID 35269749, 2022). "The majority of studies utilized Palbociclib, which is the most frequently used CDK4/6 inhibitor in cancer clinical trials." (PMID 35936751, 2022).